MGMT (O-6-methylguanine-DNA methyltransferase)
Diseases named in the same sentence as MGMT in open-access papers (continued):
Sharing a sentence is not in itself a finding about the gene and the disease.
glioma (continued). "In our series, glioma patients with methylated MGMT sequences were seen as strong prognostic factor in terms of better OS and PFS of 40 and 23.9 months versus 6.7 and 3.3 months in unmethylated MGMT respectively (p = 0.000) which is in accordance with previous reports." (PMID 29712977, 2018). "Methylation of MGMT gene promoter leads to epigenetic silencing of MGMT in glioma cells." (PMID 30327965, 2018). "Moreover, CEST contrasts have been shown to be sensitive to histopathological features of gliomas such as tumor grade, isocitrate-dehydrogenase (IDH) -mutations and MGMT promotor status." (PMID 29983895, 2018). "We evaluated the efficacy 131I-VCN in prolonging the progression-free survival of study animals in two distinct xenograft models of glioma that are devoid of O-6-methylguanine methyltransferase (MGMT) expression (i.e., U87 and U251) and therefore sensitive to TMZ." (PMID 30413113, 2018). "The cohort had several clinical and molecular characteristics: age ≥ 80 years (26.4%), lower-grade glioma (18.6%), preoperative KPS scores below 70 (51.4%), resection (34.3%), adjuvant RT + TMZ (68.6%), MGMT promoter methylation (48.6%), IDH1/2 mutation (7.7%) and TERT promoter mutation (60.9%)." (PMID 30076584, 2018). "Various postulations are reported explaining this survival benefit and one such hypothesis is silencing of MGMT gene induced by the “glioma-CpG island methylator phenotype (G-CIMP)” induced by mutant IDH though another report contradicted the same." (PMID 29439493, 2018). "We used two glioma cell lines with unmethylated and methylated the MGMT gene promoter." (PMID 30450051, 2018). "The frequency of MGMT methylation status has shown discrepancies in glioma across the globe." (PMID 29712977, 2018). "We characterized the MGMT promoter methylation status of four in vitro glioma models using methylation-specific PCR as either MGMT promoter-methylated (GBM1, JHH520) or -unmethylated (GBM10, SF188) supported by relatively low (GBM1, JHH520) or high (GBM10, SF188) IC50 values of TMZ." (PMID 29854309, 2018). "Besides, the methylation level of MGMT promoter is the most important indicator to assess TMZ sensitivity in glioma treatment, and down-regulated MGMT can substantially restore TMZ chemosensitivity in vitro and in vivo." (PMID 30498431, 2018). "The MGMT gene is epigenetically inactivated by DNA methylation in colorectal cancers, gastric cancers, head and neck squamous cell carcinomas, non-small cell lung cancers and most prominently in gliomas." (PMID 29649096, 2018). "Additionally, pre‐treatment with different BMs was also able to potentiate the TMZ action in glioma cell lines, probably due to other mechanism unrelated to MGMT." (PMID 29845734, 2018). "Interestingly, this study in comparison to other reports investigated the different groups of glioma cases and found synchronized pattern of both MGMT parameters with a better response to TMZ therapy and favorable long term survival." (PMID 29712977, 2018). "It was shown that glioma patients with a methylated MGMT gene had a better survival rate when treated with the alkylating agent temozolomide or other alkylating agents when compared to patients with an unmethylated promoter presumably because of increased cell killing by the chemotherapy agent." (PMID 29649096, 2018). "MGMT methylation and its protein expression were performed on same series of glioma samples." (PMID 29712977, 2018). "For example, Sept9 methylation is used as a biomarker for colorectal cancer screening, MGMT methylation is used for predicting sensitivity of gliomas to alkylating agents, and DNA methylation panel is used to characterize tissue origin of un-identified cancers." (PMID 30249192, 2018). "The main mechanism of resistance in glioma is increased MGMT activity." (PMID 29845734, 2018). "Therefore, we thought that TOPK promoting TMZ resistance was probably through other mechanism besides MGMT mechanism in glioma cells." (PMID 29487691, 2018).
glioma (continued). "The prognostic benefit of MGMT promoter methylation and genotypes on gliomas patients is marginal." (PMID 28575062, 2017). "Another study showed that the downregulation of DNMT1 by small interfering RNA could also lead to decreased MGMT expression and the subsequent sensitization of glioma cells to TMZ/Taxol." (PMID 28297578, 2017). "However, further investigation needs be performed to reveal the relation between N-cadherin or other EMT markers/inducers and key parameters for new 2016 WHO glioma classification, such as IDH1 mutation, 1p/19q co-deletion or MGMT promoter methylation." (PMID 28851312, 2017). "However, the median methylation level of MGMT in high-grade glioma was 71.75% (IQR, 63.75%–75.10%) compared to 56.55% of low-grade tumors (IQR, 52.33%–65.48%, P<0.01)." (PMID 29100349, 2017). "The DNA repair enzyme MGMT is frequently methylated in glioma, methylation of the CpG islands of the MGMT gene prevents transcription, which may increase the sensitivity of glioma to alkylating agents." (PMID 29046615, 2017). "The targeting TfR nanoparticles could be used for an effective therapeutic strategy against GSCs, and against non-stem tumor cells, and it would provide a promising tumoricidal strategy for treating glioma displaying MGMT promoter methylation." (PMID 29088799, 2017). "The expression of CpG Island Methylator Phenotype (CIMP) by d-2HG accounts for major gene expression changes including the silencing of MGMT (O6-methylguanine DNA methyltransferase), which is a single most important determinant of glioma resistance to alkylating agents." (PMID 28346397, 2017). "Since MGMT expression is inhibited by methylation of its promoter, and MGMT promoter methylation correlates with enhanced overall survival (OS) and progression free survival (PFS), the methylation status of MGMT is used as a predictive marker for glioma therapy." (PMID 28122345, 2017). "The value of Ki67 and MGMT as independent prognostic factors in glioma was reported previously." (PMID 29026176, 2017). "As a consequence, patients affected by glioma that have been treated with the alkylating drug temozolomide show a better prognosis when MGMT expression is reduced because of promoter methylation, this observation has been confirmed by several subsequent studies." (PMID 27057640, 2016). "Methylation of CpGs sites in MGMT promoter, one of the major post-transcriptional mechanisms reducing MGMT protein expression, has been found in 40 % of cancer such as glioma and colorectal cancer and in 25 % of non-small cell lung carcinoma, lymphoma, and head and neck carcinoma." (PMID 27733166, 2016). "We found that both CD133 and MGMT were upregulated in U87 and primary glioma cells in 3D culture." (PMID 27486877, 2016). "Finally, our study indicated that Ki-67 index and MGMT protein levels, together with IDH mutation status, were predictive of prognosis in different glioma subtypes." (PMID 27120786, 2016). "In addition, known resistance factors like MGMT also seem to be preserved in the periphery of patient gliomas." (PMID 27171431, 2016). "Sox2 activation was also found in glioma cells in 3D culture, and MGMT activation may be induced by Sox2." (PMID 27486877, 2016). "MGMT promoter methylation was analyzed in paraffinized tumor samples from 83 glioma patients." (PMID 27158275, 2016). "To elucidate whether HRM is a feasible and reasonable alternative to MSP in determining the MGMT promoter methylation status and predicting the high-grade glioma therapy response, we compared HRM and MSP systematically." (PMID 27158275, 2016).
glioma (continued). "Furthermore, valproic acid was suggested to downregulate the expression of MGMT (O-6-methylguanine-DNA methyltransferase) and to sensitize human glioma cells to temozolomide and irradiation." (PMID 27556305, 2016). "Drug resistance was attributed to MGMT upregulation and enhanced glioma cell stemness." (PMID 27486877, 2016). "In the present study, an association between IDH-1R132H mut and MGMT protein levels was observed in glioma overall, but not within the glioma subtypes." (PMID 27120786, 2016). "Furthermore, studies have demonstrated the capability of adenoviruses to inhibit the expression of the DNA repair enzyme MGMT and to chemosensitize glioma cells to TMZ." (PMID 26830677, 2016). "Methylation of MGMT sensitized glioma patients to radiotherapy or combined TMZ and radiotherapy." (PMID 26967246, 2016). "Indeed, gliomas with MGMT promoter methylation were demonstrated to be more sensitive to the alkylating agent temozolomide (TMZ)." (PMID 25943885, 2015). "MGMT is an evolutionary conserved and ubiquitously expressed enzyme that is regulated by multiple mechanisms including epigenetic silencing of the MGMT gene by promoter methylation, frequently observed in gliomas and colon cancer." (PMID 26603103, 2015). "Moreover, the predictive value of the O-6-methylguanine-DNA methyltransferase (MGMT) promoter methylation status—a widely used glioma marker—was refined by HDAC4 expression level, which was significantly related to CIN in our study." (PMID 25557107, 2015). "Previous studies also reported that promoter hypermethylation of MGMT could predict low expression levels of MGMT in gliomas, despite observed discordance between promoter methylation and protein levels." (PMID 25818895, 2015). "Therefore, methylation of MGMT has become a clinically relevant predictor of response to treatment in glioma patients." (PMID 26347581, 2015). "MGMT expression is associated with a limited benefit from TMZ and methylation of its promoter was linked to improved outcomes and is currently a promising molecular prognostic marker in the glioma field." (PMID 25867026, 2015). "To determine whether the prognostic value of the five miRNA-based signature was applicable to different populations, we analyzed an independent validation set of 19 patients with MGMT promoter methylation from the Chinese Glioma Genome Atlas (CGGA) database." (PMID 26320189, 2015). "Moreover, methylation in the promoter of the O6-methylguanine methyltransferase (MGMT) gene is known as a clinical prognostic factor regarding the action of alkylating agents in gliomas." (PMID 25908947, 2015). "Glioma tissue heterogeneity may confound assessment of molecular markers such as EGFRvIII expression and MGMT promoter methylation." (PMID 25720744, 2015). "The most significant difference (P = 5 × 10−5) between the two largest clusters was loss of the terminal end of the q arm of chromosome 10 including MGMT, which occurred in 80 % of the cluster with most of the GBMs and 9 % of the cluster with primarily lower grade gliomas." (PMID 26091668, 2015). "The expression of MGMT protein is heterogeneous within the glioma tissue." (PMID 26035292, 2015). "Further analyses correlated the high expression of MGMT with the presence of a hypovascular central core of the tumor, where activation of the hypoxia inducible factor (HIF)-1α will in turn promote expression of MGMT, particularly in the hypoxic glioma stem cells niches." (PMID 26035292, 2015).
glioma (continued). "MGMT status was previously determined by using Quantitative Methylation Specific PCR (QMSP): aberrant promoter methylation was found in the 68.75% of the 32 glioma patients." (PMID 25279461, 2014). "To investigate whether age may influence abnormal DNA repair gene expression, and affect susceptibility to the development of gliomas, we assessed the association between APE1, NBN, PMS2, MGMT and PTEN mRNA expression and age." (PMID 25026297, 2014). "However, studies also show that many glioma patients with epigenetically silenced MGMT genes have increased disease-free and overall survival rates." (PMID 25198391, 2014). "Inherent resistance of high-grade gliomas to alkylating agents has often been linked to expression of the de-alkylating enzyme MGMT, which is not expressed in around half of these tumours." (PMID 25071006, 2014). "Given the findings in elderly GB patients, the methylation status of the MGMT promoter may also predict the outcomes of low-grade glioma patients treated by TMZ monotherapy." (PMID 25175833, 2014). "Other researchers have studied gliomas to determine whether MGMT promoter methylation is related to the responsiveness of a tumor to alkylating agents, and found that this methylation was associated with tumor regression and prolonged survival rates." (PMID 25198391, 2014). "First, we evaluated p-EGFR, MGMT expression levels in a panel of glioma cell lines." (PMID 24418474, 2014). "For example, DNA hypermethylation of the glutathione S-transferase pi 1 (GSTP1) gene was correlated with prostate cancer, thus serving as a diagnostic tool, while hypermethylation of O 6-methylguanine-DNA methyltransferase (MGMT) aids in decisions for therapeutic strategies for glioma." (PMID 25076963, 2014). "Indeed, miR-221 overexpression in glioma cells led to an increase in markers of DNA damage, an effect rescued by re-expression of MGMT." (PMID 24147153, 2013). "The frequency of MGMT immunopositivity increased with the glioma grade." (PMID 23946790, 2013). "However, to the best of our knowledge, no comprehensive characterization has been reported of the combined effect of epigenetic and genetic alterations on MGMT expression or its eventual clinical impact in high-grade gliomas." (PMID 23505468, 2013). "MGMT immunoreactivity was identified in 84 (55.3%) of the 152 glioma samples." (PMID 23946790, 2013). "In the present study, it was revealed that MGMT was expressed in 55.3% of glioma samples." (PMID 23946790, 2013). "Furthermore, epidermal growth factor receptor and methylguanine-DNA methyltransferase (MGMT) promotor hypermethylation were reported to be associated with histological transformation and recurrence of gliomas." (PMID 24088576, 2013). "There is ongoing discussion about the best method to assess MGMT dowregulation in gliomas for its use as predictive biomarker of response to alkylating agent therapy, including promoter methylation analysis, levels of mRNA or protein expression, or enzyme activity." (PMID 23505468, 2013). "This dependence has been demonstrated by treating glioma, leukemia, ovarian, and breast cell lines with suicide inactivators of MGMT, O6-benzylguanine (O6-BG) or 6-[(4-bromo-2-thienyl)methoxy]-9H-purin-2-amine (PaTrin-2); MGMT inhibition increased sensitivity to TMZ treatment." (PMID 24287492, 2013).
glioma (continued). "Finally, evaluation of copy number alterations involving the MGMT locus should be incorporated into future trials designed to assess the prognostic and predictive value of MGMT downregulation in patients with high-grade gliomas." (PMID 23505468, 2013). "For example, in gliomas, MGMT methylation patterns are predictive and may help guide treatment options." (PMID 24367530, 2013). "While MGMT is also expressed in several non-CNS cancers, it is currently unknown whether EMT can induce MGMT expression." (PMID 23818228, 2013). "MGMT is another relevant example of a DNA repair regulator gene undergoing methylation-mediated inactivation in gliomas, even in an early phase.MGMT hypermethylation has been reported in gliomas grade I to IV from 20 to 90% depending on the histological subtype." (PMID 22778947, 2012). "As a result, a wide range of reported glioma MGMT methylation frequencies can be seen." (PMID 22390413, 2012). "As a result, O6-BG enhances TMZ cytotoxicity in MGMT-proficient glioma cells both in vitro and in vivo but not in MGMT-deficient cells." (PMID 22530127, 2012). "It has been proposed that MGMT methylation may represent an epiphenomenon of CIMP in the context of grade III glioma." (PMID 22810491, 2012). "This study has provided further evidence that the histological transformation and progression of gliomas may be associated with the inactivation of the EGFR and MGMT genes." (PMID 22264301, 2012). "However, the best-known example is the role of promoter hypermethylation of the DNA-repair gene MGMT (O6-alkylguanine-DNA alkyltransferase) in the response of gliomas to alkylating agents." (PMID 22852080, 2012). "Furthermore, increased MGMT expression is well correlated with in vitro and in vivo glioma resistance to TMZ." (PMID 22530127, 2012). "Even though the first studies suggesting that MGMT promoter hypermethylation was an important molecular marker in high-grade gliomas were published almost a decade ago, the extent of its positive prognostic and predictive value in the different grades of gliomas remains to be determined." (PMID 22390413, 2012). "Consequently, MGMT activity and the promoter methylation status of the MGMT gene (indicators of O6MeG repair capacity and MGMT protein expression, respectively) are used as predictive markers for the response of gliomas to TMZ." (PMID 22073281, 2011). "We hypothesized that MGMT promoter hypermethylation reflects global DNA hypermethylation in gliomas." (PMID 21829728, 2011). "This direct correlation between MGMT and reduced angiogenicity and tumorigenicity may suggest a role for sunitinib in combination with standard treatment in MGMT-positive gliomas." (PMID 22295207, 2011). "In addition, some studies have shown that MGMT promoter methylation and MGMT protein expression cannot be used interchangeably to predict patient survival or glioma chemosensitivity." (PMID 21269507, 2011). "Four-hundred and sixteen adult patients with newly diagnosed glioma were included over a 3-year period and tumour suppressor genes, oncogenes, MGMT and hTERT expressions, losses of heterozygosity, as well as relevant clinical and imaging information were recorded." (PMID 18506188, 2008).